CECR3 (cat eye syndrome chromosome region, candidate 3)
Gene: Long non-coding RNA gene on chromosome 22 (17,256,859 to 17,266,822, reverse strand). Ensembl gene ENSG00000241832.
Diseases named in the same sentence as CECR3 in open-access papers:
CECR3 is named in the same sentence as 1 disease in open-access papers, as found by Europe PMC text mining. Sharing a sentence is not in itself a finding about the gene and the disease.
CECR3 shares sentences with these, for which no sentence is quoted: cat-eye syndrome (1 paper).